INS (insulin)
Diseases named in the same sentence as INS in open-access papers (continued):
Sharing a sentence is not in itself a finding about the gene and the disease.
Hypoglycemia (continued). "As well, titration of insulin so as to achieve accepted targets for HbA1c while minimising the risk of hypoglycaemia and weight gain, may be problematic with conventional insulin regimens." (PMID 19152692, 2009). "So although many reports and numerous editorials have called tight glycemic control strategies into question citing the inherent risk of hypoglycemia and association with mortality, they have largely overlooked performance characteristics of the IV insulin protocols used in the studies." (PMID 19822000, 2009). "However, due to technological limitations, injections of inappropriate insulin doses cause frequent episodes of mild hypoglycaemia which lead to the blunting of the SAR (BSAR)." (PMID 19442093, 2009). "In fact, their key hallmark is uncontrolled insulin secretion, despite hypoglycemia." (PMID 19545371, 2009). "• Intensive insulin therapy was associated with an increased risk of severe hypoglycaemia." (PMID 18799004, 2008). "The increased claims and the associated costs of SMBG test strips for beneficiaries receiving insulin could be due to increased risk of hypoglycemia arising from insulin use and use of results to regulate insulin regimen." (PMID 18501012, 2008). "Insulin challenge tests can be equally dangerous due to risk of hypoglycemia." (PMID 18426576, 2008). "Tumours may cause hypoglycemia by different mechanisms; functional insulinomas produce insulin and thus lower blood glucose." (PMID 18485198, 2008). "In several studies, these analogue formulations provided better or equivalent postprandial glycaemic control with a reduced risk of hypoglycaemia compared with premixed human insulin along with greater flexibility and convenience of injecting immediately before meals." (PMID 18657196, 2008). "Furthermore, the use of newer, simple patient-driven algorithms permits patients to titrate insulin to goal with a reduced risk of hypoglycemia." (PMID 18279520, 2008). "Because L-arginine increases the secretion of insulin review articles have stated that L-arginine may cause hypoglycemia." (PMID 18545693, 2008). "The German multicentre Efficacy of Volume Substitution and Insulin Therapy in Severe Sepsis (VISEP) study of IIT for septic patients in multidisciplinary ICUs was prematurely stopped due to a higher risk of hypoglycaemia using IIT compared with conventional insulin therapy (17.0% versus 4.1%)." (PMID 18939991, 2008). "For example, while the clear majority of PCPs agreed that the benefits of insulin outweighed the risks of hypoglycaemia for most patients, 44% agreed that the risk of hypoglycaemia made them reluctant to prescribe insulin to most patients who were ≥ 85 years old." (PMID 18393965, 2008). "While aggressive insulin therapy that maintains glucose levels near the normal range reduces the risk of secondary complications, patients often find such control difficult to achieve and suffer an increased risk of hypoglycemia." (PMID 17201925, 2007). "However, a number of trials have demonstrated that greater improvements in FBG and/or HbA1c can be achieved with insulin glargine vs. NPH insulin, with a lower risk of hypoglycaemia, even with intensive insulin titration regimens." (PMID 17997807, 2007). "The cause of the dissociation between large doses of insulin and the severity of subsequent hypoglycaemia remains unclear." (PMID 17963523, 2007). "Moreover, there is a risk of exposing the patient to the risk of hypoglycemia if excessive doses of insulin are administered." (PMID 15916471, 2005). "However, infusing insulin in order to lower glucose levels bears the risk of inducing life-threatening hypoglycemia, especially in sedated patients admitted to an intensive care unit (ICU)." (PMID 16359559, 2005). "This might be because of transient upregulation of the PEPCK gene at birth, resulting in increased production of (pro)insulin that caused hypoglycaemia." (PMID 15679918, 2004).
Hypoglycemia (continued). "Therefore, the clonal expansion may contain more than enough insulin to cause hypoglycaemia, if released to the blood." (PMID 41488993, 2026). "Patients receiving exogenous insulin may easily develop hypoglycemia due to glucagon deficiency." (PMID 41347115, 2026). "However, our study suggested an association between prolonged fasting before surgery and an increased risk of hypoglycemia: prolonged fasting might interfere with patients’ metabolic status and insulin sensitivity." (PMID 40692592, 2025). "Insulin therapy may be more suitable for patients requiring more aggressive glycemic control or with advanced beta-cell dysfunction, whereas oral agents may be preferred for those with lower hypoglycemia risk or weight management concerns." (PMID 40959330, 2025). "Given its fundamental role in energy metabolism, we hypothesize that FAO suppression in neonates born to anemic mothers may increase the risk of hypoglycemia, metabolic inflexibility, and long-term metabolic disturbances, including insulin resistance, lipid accumulation, and cardiac inefficiency." (PMID 40287617, 2025). "However, continuous subcutaneous insulin infusion (CSII) therapy using an insulin pump has been shown to provide precise insulin delivery, improved glycemic outcomes, and reduced risk of hypoglycemia, making it an increasingly popular option for patients with T1DM." (PMID 41473654, 2025). "Furthermore, insulin was widely prescribed, heightening the risk of hypoglycemia." (PMID 40128462, 2025). "38.6% of the participants were noted to have injection phobia.55% cited fear of risk of hypoglycaemia with insulin therapy.30.2% cited fear of weight gain with insulin use.14.8% believed that their health will deteriorate with insulin use.31.7% believed that insulin injections were painful." (PMID 40336418, 2025). "Importantly, it also minimizes the so-called “shoulder effect,” a pharmacodynamic phenomenon observed with premixed insulins in which overlap between intermediate-acting and rapid-acting components leads to a prolonged insulin peak and increases the risk of postprandial hypoglycemia." (PMID 41293743, 2025). "Therefore, some studies suggest that CIPII may reduce the risk of hypoglycemia compared to subcutaneous insulin as well as improving patient satisfaction." (PMID 40995084, 2025). "Additionally, β2-receptor blockade in the liver and skeletal muscle may reduce glycogenolysis and insulin-mediated glucose uptake, increasing the risk of hypoglycemia or impaired exercise tolerance, especially in diabetic or insulin-resistant patients." (PMID 41463309, 2025). "Additionally, insulin use within these HbA1c ranges further exacerbates hypoglycemia risk." (PMID 41040859, 2025). "If this feature is combined with a manual prandial bolus insulin reduction initiated by the user (e.g. 25–33% reduction) prior to activity, then glucose will likely rise and result in automated insulin delivery by the system, thereby increasing hypoglycaemia risk during PA." (PMID 39653802, 2025). "Insulin overdose may cause hypoglycemia, leading to coma or potentially death." (PMID 40807234, 2025). "Furthermore, the introduction of GLP1RAs enabled a reduction or suspension of concomitant insulin therapy in, respectively, 61 and 22% of individuals, thereby decreasing the risk of hypoglycemia and eliminating an additional factor negatively impacting body weight." (PMID 40496570, 2025). "Significantly, the expert opinion of 97.1% of respondents was that CGM devices should be reimbursed for any person with T2D on any insulin therapy, and 34.3% indicated that CGM should be prescribed for any person with T2D at risk of hypoglycaemia on any therapy, whether insulin or non‐insulin." (PMID 39676327, 2025). "Similarly, those using continuous subcutaneous insulin infusion may find it beneficial to reduce basal rates by 20% at bedtime for 6 hours after afternoon exercise to mitigate the risk of nocturnal hypoglycemia." (PMID 38954647, 2025).
Hypoglycemia (continued). "However, for most elderly diabetic patients, premixed insulin may increase the risk of hypoglycemia." (PMID 40260392, 2025). "CGM connectivity, smart bolus calculator, hypoglycemia and exercise risk warnings, and biweekly treatment optimization; cloud-based infrastructure for updates and monitoring; communication between smart insulin pens and the app to record insulin administration." (PMID 40051514, 2025). "Moreover the hypoglycaemia risk is higher at insulin initiation and may hinder compliance and continuation of insulin therapy." (PMID 40190894, 2025). "These agents lower glucose through glucose-dependent insulin secretion, glucagon suppression, delayed gastric emptying, and appetite reduction, significantly decreasing the risk of hypoglycemia.In addition, dapagliflozin may be added to support weight loss and blood pressure control." (PMID 41585798, 2025). "Interestingly, myricetin exerts its insulin secretory potential in a dose-dependent manner exclusively at the stimulatory glucose concentration, suggesting a reduction in the hypoglycemia and other adverse effects caused by already marketed drugs like sulfonylurea and glinide." (PMID 40564164, 2025). "Beyond hypoglycemia, this study also identified visual impairment and retinopathy as significant signals within eye disorders, indicating that eye complications could be an additional safety concern associated with prolonged insulin use." (PMID 40997126, 2025). "However, insulin therapy requires frequent monitoring and poses a significant risk of hypoglycemia." (PMID 40868089, 2025). "Additionally, the increased risk of nocturnal hypoglycemia may stem from variations in insulin metabolism, with peak activity occurring during the overnight period." (PMID 40186384, 2025). "However, high doses of insulin may increase the risk of hypoglycemia, which is a common complication of CFRD." (PMID 40533897, 2025). "Thus, insulin-therapy-induced hypoglycemia may increase the risk of mortality in diabetic patients following PCI." (PMID 41464751, 2025). "Including insulin in parenteral mixed solutions presents challenges in effectively controlling insulin infusion rates owing to drug interactions or precipitation, resulting in significant fluctuations in blood sugar levels and an increased risk of hypoglycemia." (PMID 40568192, 2025). "Furthermore, established treatments for acute hyperkalaemia—such as insulin–dextrose infusions—have been shown to be associated with significant morbidity, particularly with repeated doses in which iatrogenic hypoglycaemia is associated with increased rates of death." (PMID 39669394, 2024). "Half of the subjects were being treated with anti-hyperglycemic agents that could be associated with severe hypoglycemia (sulfonylureas, glinides, and insulin), but only 1 subject who was being treated with a glinide showed severe renal dysfunction (eGFR ≤ 30 mL/min/1.73m2)." (PMID 39049060, 2024). "Administration of exogenous insulin in T1D therapy exacerbates the dysregulation of alpha cells and, in cases where they are not able to mount an appropriate response, may cause life-threatening hypoglycemia." (PMID 39594662, 2024). "Treatment with insulin, aiming for currently recommended targets, may also cause hypoglycemia." (PMID 39039540, 2024). "An association between lower insulin dose at the end of the baseline data collection period of weeks 1 to 6 and subsequent hypoglycaemia may be expected due to dose adjustments in response to a higher incidence of hypoglycaemia events during this period." (PMID 38795153, 2024). "Therefore, hypoglycemia in CF may be a result of delayed first-phase insulin secretion, glucagon deficiency, undernourishment, gastrointestinal disorders, liver disease, and incretin dysregulation." (PMID 38541202, 2024). "Insulin therapy may cause frequent episodes of hypoglycaemia in FBS patients." (PMID 38365697, 2024).
Hypoglycemia (continued). "Furthermore, a reduced risk of insulin need (RR = 0.29, CI: 0.13–0.68), preeclampsia, or gestational hypertension (RR = 0.38, CI: 0.2–0.71), preterm birth (RR = 0.44, CI: 0.22–0.88), and neonatal hypoglycemia (RR = 0.12, CI: 0.03–0.55) was also shown." (PMID 39336874, 2024). "In addition, fracture risk may also depend on hypoglycemia-induced falls, especially those related to insulin or sulfonylurea, as well as complications of T2DM." (PMID 38541119, 2024). "While the relatively small sample size may limit the statistical power to detect more subtle differences, particularly in outcomes such as GV or hypoglycemia risk, this study serves as a pilot investigation to explore the impact of different insulin administration timings." (PMID 39588847, 2024). "Additionally, potential drug interactions with ginger supplements have been proposed, including hypoglycemia from an additive effect of insulin or metformin use and an increased risk of bleeding with aspirin use because of decreased platelet aggregation from thromboxane synthetase inhibition." (PMID 39343171, 2024). "Continuing the IV insulin infusion without reducing its rate when glargine administration overlaps by several hours means the child is exposed to greater insulin action, which may increase the risk for hypoglycemia while on IV insulin, and it is consistent with our observation." (PMID 39136541, 2024). "Additionally, we observed a high risk for hypoglycemia, which mimics findings in adults, and we hypothesize that this may also be due to insulin use." (PMID 38659064, 2024). "Furthermore, if an injectable therapy is needed to reduce HbA1c, a GLP-1 RA should be considered in most patients prior to insulin, as they allow lower glycemic targets to be reached with a lower injection burden and lower risk of hypoglycemia and weight gain than with insulin alone." (PMID 38767675, 2024). "Given this, and after having shown that TRPC5 is critical to the elevated adrenaline during insulin-induced hypoglycemia, the authors tested whether genetic loss of TRPC5 in RVLM neurons is critical to the autonomous counter regulation maintenance and found that is not." (PMID 39487352, 2024). "In addition, insulin therapy is associated with several side effects such as hypoglycemia and weight gain, which may lead some patients to lower their insulin dose." (PMID 39518671, 2024). "Those wrong values could potentially lead to false analyses and health recommendations by the app and hence might lead to lower clinical outcomes or, in a worst-case scenario, to high-risk situations for the patient, e.g., in hypoglycemia, if too much insulin is injected." (PMID 39251786, 2024). "Besides the current case, these included patients feigning coagulopathy by surreptitious intake of warfarin, hypoglycemia due to self-injection of insulin, diarrhea caused by surreptitious laxative abuse and repeated induction of abscesses by self-injection of stool into the abdominal wall." (PMID 38376552, 2024). "However, there may be an increased risk of level 1 hypoglycemia during IV insulin administration in patients whose glargine administration overlaps with IV insulin administration." (PMID 39136541, 2024). "The pharmacological action of GLP-1RA is based on the stimulation of glucose-dependent insulin secretion, glucagon secretion reduction, and slowing gastric emptying, resulting in improved glycemic control and modest weight loss with a reduced risk of hypoglycemia." (PMID 38524632, 2024). "However, the risk of hypoglycemia, other side effects such as excessive weight gain, and the fear of daily injections can limit insulin use in patients, and these shortcomings have prompted researchers to refine insulin formulations." (PMID 39629047, 2024).
Hypoglycemia (continued). "Hypoglycemia can be serious–more common than hyperglycemia as a cause of hospital admissions among Medicare beneficiaries in 1999–2011, and hypoglycemia related to use of insulin or sulfonylureas was among the most frequent causes of drug-related adverse events in emergency departments in 2013–2014." (PMID 39546502, 2024). "Given that those with loss of function variants in KCNQ1 may be prone to post-prandial hypoglycemia due to increased insulin release from the pancreas, increased vigilance is warranted when prescribing beta-blockers to those with both KCNQ1 variants and the CPT1A p.P479L variant." (PMID 38884101, 2024). "However, challenges and barriers associated with insulin therapy, including the risk of hypoglycemia, weight gain, injection anxieties, and logistical inconveniences, may discourage its initiation." (PMID 38969701, 2024). "Patients on insulin therapy who begin a preoperative pathway with initial reduction of caloric intake may already undergo a reduction in insulin requirements and frequent dose adjustments to eliminate the risk of hypoglycemia." (PMID 38942960, 2024). "Given that the R-time was unchanged during hypoglycemia on both test days and that administration of insulin previously has been associated with anti-inflammatory effects, we speculate that the hyperinsulinemic clamp technique may have contributed to these anticoagulant effects after 24 hours." (PMID 38642404, 2024). "To test whether the lack of adrenaline rise in TRPC5-deficient animals causes the more severe insulin-induced hypoglycemia, we aimed to prevent aggravated hypoglycemia by supplementing adrenaline shortly after the insulin application in an adrenaline rescue experiment." (PMID 39375537, 2024). "The reason may be sulfonylureas' and insulin's significantly higher hypoglycemia risk." (PMID 39431844, 2024). "While the risk of hypoglycemia was nearly the same for both cohorts, other factors were associated with hypoglycemia in the univariate and multivariable logistic regression analyses, including age, heart failure, and receiving dialysis or a second dose of insulin." (PMID 39274318, 2024). "Furthermore, neither of these SSRIs stimulated basal insulin secretion at 2 mM glucose, which is clinically important because drugs that increase insulin secretion at low glucose levels may cause hypoglycaemia in the fasting state." (PMID 38888050, 2024). "Additionally, alcohol intoxication impairs cognitive function, which may result in missed insulin doses, miscalculated dosages, or delayed blood glucose monitoring, further exacerbating the risk of hypoglycemia." (PMID 39286453, 2024). "However, cognitive dysfunction issues might affect eating patterns and/or cause a delay in recognizing symptoms of mild hypoglycemia associated with insulin use, which in turn can lead to severe hypoglycemia." (PMID 38673407, 2024). "The results showed that insulin-exposed neonates had a higher incidence of hypoglycemia than metformin-exposed neonates (RR 0.65; 95% CI 0.52, 0.81; I2 = 22%; p = 0.0001) and that metformin lowered the risk of neonatal hypoglycemia by 45% compared with the insulin-exposed group." (PMID 36593391, 2023). "Similarly, an individual receiving higher basal insulin may eventually need a carbohydrate snack at bedtime to avoid the risk of nocturnal hypoglycemia." (PMID 40303252, 2023). "Interestingly, experimental studies have shown that adipocytes of SGBS patients are more sensitive to insulin stimulation, which may cause increased glucose uptake and thereby cause hypoglycemia." (PMID 37065762, 2023). "In addition to dementia, we found other predictors of hypoglycaemia were age ≥65 years, being a man, T1DM, smoking, BMI, history of hypoglycaemic events, arrhythmia, and the use of insulin and sulfonylureas, which have a statistically significant effect on hypoglycaemia risk (p-value < 0.05)." (PMID 37476614, 2023).